MITF (melanocyte inducing transcription factor)
Diseases named in the same sentence as MITF in open-access papers (continued):
Sharing a sentence is not in itself a finding about the gene and the disease.
melanoma (continued). "Collectively, reduction in MITF levels had no dramatic effect on proliferation rate in melanoma cell lines, probably partly because the degree of knockdown left some MITF level which was sufficient for proliferation." (PMID 29369499, 2018). "Indeed, at advanced melanoma stages, as a consequence of SCD5 restored expression we evidenced MITF up-regulation paralleled by miR-221&222 decreases." (PMID 29484133, 2018). "Since we observed a close correlation between the Wnt3a-CM or PKF115–584 treatment and the expression of pigmentation related genes (DCT, TYR, TYRP1, MITF) in our SKMEL28 microarray data, we analyzed the TCGA melanoma RNAseq expression data concerning MLANA expression." (PMID 29454361, 2018). "MITF has been described as an oncogene in melanoma, but it has not been previously studied or reported in GISTs." (PMID 29885053, 2018). "Melanomas harboring constitutively active BRAF protein, or about half of all melanoma cases, showed low levels of PGC1α due to BRAF suppression of the melanocyte lineage factor, MITF, which directly regulates PGC1α." (PMID 29361779, 2018). "MITF is amplified in a subset of human melanomas, which cooperates with oncogenic BRAF V600E to transform normal melanocytes." (PMID 30544544, 2018). "The MITF gene was located in this QTL interval, but was discarded as a susceptibility gene, even though its involvement in porcine melanoma tumors makes no doubt." (PMID 29963229, 2018). "The aim of the study was to evaluate any possible correlation between mutations in main growth-controlling genes (BRAF, NRAS, CDKN2A) and copy number variations in frequently amplified candidate genes (MITF, EGFR, CCND1, cMET, and cKIT) during melanoma initiation and progression." (PMID 29492214, 2018). "This would support a recent publication, which found that MITF is required for melanoma cell migration and invasion independent of BRN2, meaning in MITFhigh and MITFlow melanoma cells." (PMID 29454361, 2018). "Considering the reduced spreading of melanoma cells overexpressing SCD5 and the increased expression of MITF, we evaluated whether miR-221&222 levels were modulated by the presence of SCD5." (PMID 29484133, 2018). "Although some controversy exists regarding its oncogenic role in melanoma, MITF has been defined as a “lineage survival oncogene” with no data pointing out at a tumor-suppressive function." (PMID 30310055, 2018). "No significant decrease was observed in patients with melanoma recurrence (p = 0.197 for MITF-m; p = 0.325 for TGFB2)." (PMID 29156734, 2017). "Likewise, it was reported that in 501mel melanoma cells depleted of TFAP2A, the expression levels of MITF were unchanged compared to control cells, while expression of TYR, encoding the rate limiting enzyme of melanin synthesis, was decreased." (PMID 28249010, 2017). "We initially focused the analysis to on variants in genes known to cause familial malignant melanoma, but we did not identify any clearly causative variation in these genes (BAP1, CDK4, CDKN2A, MC1R, MITF and PTEN)." (PMID 28623311, 2017). "We could further confirm the mutual exclusion of MITF/EDNRB and AXL/EDNRA expression in a panel of melanoma cell lines." (PMID 28606996, 2017). "In particular, CD271 overexpression did not prevent MITF expression in human melanoma cells in vivo." (PMID 29215016, 2017). "This seems to indicate that MITF is not sufficient to rescue phenformin cytotoxic effects in melanoma." (PMID 28036292, 2017). "For instance, a recent paper showed that induction of ATF4 in melanoma cell lines inhibits MITF expression, but does not affect invasive potential." (PMID 28545079, 2017). "We initially identified melanoma cell lines that had expression of both BRN2 and MITF." (PMID 28883623, 2017).
melanoma (continued). "The observation of a melanocyte-like phenotype was supported by the fact that shRNA-Tsc2 + Cdkn2a sphere cells that were differentiated in neural-crest differentiation medium showed similar positive staining for CATHEPSIN K, PMEL, MITF and MART-1 to the B16F1 melanoma cell line." (PMID 29133867, 2017). "Cordycepin was reported to inhibit α-MSH and IBMX induced melanin biosynthesis by inhibiting melanin synthesis related enzymes, such as tyrosinase, TRP-1, and TRP-2, suppressing CREB and MITF activity, and activating the PI3K/AKT pathway in B16F10 melanoma cells." (PMID 28114924, 2017). "To test whether miR-26a targeting MITF was responsible for the reduced cell viability observed from miR-26a mimics, we knocked down the MITF gene expression in both SKMEL-28 and WM1552C melanoma cell lines using siRNAs." (PMID 28698805, 2017). "Indeed, recent reports have suggested that melanoma cells switch back to the embryogenetic program initiated during neural crest formation by means of several factors as PAX3 and MITF." (PMID 29156734, 2017). "Interestingly, double staining experiments clearly showed that MITF and BRN-2 expression in melanoma cells is mutually exclusive." (PMID 29156643, 2017). "MITF regulates the expression of numerous genes involved in the regulation of cell proliferation, such as B-cell lymphoma 2 (BCL2), cyclin-dependent kinase 2 (CDK2), cyclin D1, and p21, and promotes cell proliferation in melanocytes and melanomas." (PMID 28880216, 2017). "In addition to the finding that melanoma cells could be classified by these two descriptors, several groups have described that melanoma cells can reversibly switch between these two subsets either by direct genetic manipulation of MITF or environmental cues like TGF-β, inflammation, and hypoxia." (PMID 28545079, 2017). "In addition, melanoma cells that endogenously express MITF were transfected with OCT4-Flag, and immunoprecipitation was done using antibody against MITF." (PMID 29044103, 2017). "To conclude, we show here that phenotype switching in melanoma regulates ILEI expression, and knockdown of ILEI attenuates invasive potential in MITF-low invasive melanoma cells, but does not affect chemoresistance or MITF expression." (PMID 28545079, 2017). "As expression of MITF and BRN2 is mutually exclusive in patient tumors and xenografts, we investigated the role of each of these transcription factors in the phenotype of the melanoma tumor cell population." (PMID 28883623, 2017). "Co-occupancy of enhancers by MITF and TFAP2A was also reported in human melanoma cell lines." (PMID 28249010, 2017). "Moreover, because MITF acts as an essential regulator of melanoma cell viability and survival 14, the reduced expression of DNA PKC in IGR37 cells was accompanied by a decline in the MITF expression." (PMID 28608446, 2017). "Importantly, in melanoma FRA1 and MITF expression are mutually exclusive and low FRA1 expression indicates a cell state with high MITF expression." (PMID 28606996, 2017). "Melanoma spheres were generated using A2058− empty, A2058− BRN2, or A2058− MITF stable cell lines." (PMID 28119061, 2017). "Collectively, our data support the hypothesis that MiTF and the FANC proteins operate within one pathway to ensure DNA integrity, high proliferation and survival in melanoma." (PMID 27827420, 2016). "To identify potential target(s) for therapeutic intervention in a significant proportion of melanomas that harbor dual mut-BRAF and MITF amplification (MITFAmp), we developed a multi-step integrative target identification approach—drug-effected integrative identification of target(s) (DEFINIT)." (PMID 26962685, 2016). "In this regard, inhibition of Akt in melanoma cells increases melanogenesis pathway, by inducing MITF, meanwhile the inhibition of ERK did not." (PMID 27206672, 2016). "Moreover MITF-driven ELS biogenesis results in stimulation of Wnt signaling from the MVBs, which in turn support melanoma proliferation." (PMID 27896217, 2016).
melanoma (continued). "From a list of 113 genes shown to be up-regulated by MITF in melanoma, 23 were up- and 20 down-regulated in NuKO cells, which would suggest that Ap4A-mediated MITF or USF2 activation is not prominent in our data." (PMID 27144453, 2016). "However, in zebrafish mutants where a temperature shift lowers levels of functional MITF (possibly compatible with proliferation), BRAFV600E efficiently induces melanoma." (PMID 27200346, 2016). "Therefore, we set to test the functional impact of CPEB4 in the levels and polyadenylation status of both, MITF and RAB72A in additional melanoma cell lines and in tissue specimens (respectively)." (PMID 27857118, 2016). "Moreover, we observe that, similarly to the consequence of MiTF downregulation, FANC pathway silencing alters proliferation, migration and senescence of human melanoma cells." (PMID 27827420, 2016). "To limit off-target effects, we did not modify cells genetically but instead we have chosen patient-derived melanoma populations with originally distinct molecular characteristics: (i) BRAFWT, MITF-Mhigh/NF-κBlow, (ii) BRAFV600E, MITF-Mhigh/NF-κBhigh, (iii) BRAFV600E, MITF-Mlow/NF-κBhigh." (PMID 26824319, 2016). "Cells of a potential subset of melanoma, which is indicated by the bimodal distribution, may use the up-regulation of SOX5 to repress MITF in order to prevent its inhibitory effect on proliferation." (PMID 26927636, 2016). "To identify MITF regulators distinctively and differentially active in melanoma cells, we investigated the expression dataset of the NCI-60 panel comprised not only of melanoma cells but also of cells from several other tumor entities." (PMID 26927636, 2016). "The melanoma SK-Mel-103 was selected for an initial screen, as a well-known example of MITF-negative amelanotic melanoma cells." (PMID 27857118, 2016). "However, it was also possible that PN could elevate the MITF level because it is an inhibitor of NF-κB and the gene expression reciprocity between NF-κB and MITF was reported in melanoma cell lines as modulating intrinsic sensitivity of melanomas to inhibitors of the BRAF/MEK/ERK pathway." (PMID 26824319, 2016). "Furthermore, ZEB1 knockdown decreased the viability of resistant melanoma cells in both MITFlow and MITFhigh contexts, suggesting that ZEB1 partly functions through MITF‐independent mechanisms." (PMID 27596438, 2016). "Moreover, combined treatment with MAPK pathway and HDAC inhibitors suppressed MITF expression and melanoma resistance offering a novel clinical strategy to achieve more durable control of some BRAFV600E melanomas." (PMID 26824319, 2016). "We applied a computational approach we developed earlier to identify MITF transcriptional regulators that could predict changes in MITF expression levels over a set of different cancer types (NCI-60 panel) and a set of melanoma samples." (PMID 26927636, 2016). "Although the tumor cells were partly positive for the microphthalmia transcription factor (MiTF), no immunoreactivity for the human melanoma black 45 and melan-A was seen." (PMID 27998309, 2016). "Low levels of MITF and high levels of AXL may predict melanoma resistance to BRAFi, and the resistance may involve (re)activation of MAPK or PI3K/mTOR signaling." (PMID 26918352, 2016). "An inverse relationship between MITF and ERBB3 protein expression levels was observed in our cell panel, and this was particularly evident in the immortalized melanocyte cell line Hermes 4C, and in the melanoma cell lines WM983B and WM115." (PMID 27391157, 2016).
melanoma (continued). "Several transcription factors, including ZEB1/2, SNAIL1/2, TWIST1/2, MITF and JUN, have been shown to play key roles in melanoma EMP-like processes; however, the mechanisms by which internal and micro-environmental signals are integrated to modulate transcriptional activity are not fully understood." (PMID 27852308, 2016). "On the basis of overlapping marker genes and proteins (for example, FN1 upregulation and MITF downregulation), we identified a biological similarity to a reported phenotypic switch in (BRAF inhibitor-naive) melanoma, as reported in a series of publications by Hoek, Dummer and colleagues." (PMID 27648299, 2016). "Thus, PAX3, a well-known transcriptional regulator of MITF, is upregulated during MAPKi treatment, which is also seen within 48 hr in a panel of BRAF mutant melanoma cell lines." (PMID 26977879, 2016). "However, also low MITF/AXL and MITF/EGFR ratios have been suggested to be involved in early resistance to vemurafenib in a subset of melanomas." (PMID 27391157, 2016). "Indeed, when melanoma spheres are exposed to embryonic fibroblast‐conditioned medium, the otherwise predominant co‐expression of BRN2 and MITF switches to an inversely correlated expression." (PMID 25818589, 2015). "Next, we addressed whether there is a direct mechanistic link between MITF and c-Jun/FOSL1 that explains their anti-correlated expression found in melanoma cell line panels." (PMID 26530832, 2015). "In line with this, SOX9 inhibits melanoma cell growth and induces the expression of MITF and p21CIP1, but the p21CIP1 growth inhibitory effect is largely independent of MITF." (PMID 25818589, 2015). "Depletion of BRN2 from melanoma cells has consistently been described to reduce MITF levels, indicating that BRN2 is required to drive MITF expression." (PMID 25818589, 2015). "As HIF1α is a MITF target and can be expressed in melanoma cells not only under hypoxic conditions, this mechanism constitutes an interesting negative feedback loop regulating MITF expression." (PMID 25433395, 2015). "We propose that interfering with WNT5A signaling will affects PI3K-AKT and the β-catenin-MITF-EGFR axis, which would make Box-5 therapy useful for not only BRAFi-resistant melanomas but also melanomas that do not carry BRAF mutations." (PMID 26393652, 2015). "This study revealed a key regulatory mechanism in melanoma, where BRAFV600E may play dual roles as a positive regulator of the MITF pathway and as a negative regulator of the TGFB1 pathway in the initiation of melanoma development." (PMID 25890285, 2015). "NURF is therefore present in all types of melanoma cells irrespective of MITF expression and their tumourigenic properties." (PMID 26440048, 2015). "MITF and BRN2 are two transcription factors found to be mutually exclusively expressed in melanoma cells, marking highly proliferative versus highly invasive melanoma cells, respectively." (PMID 25880082, 2015). "Another study suggests, however, that intrinsically resistant melanomas can be characterized by low expression/activity of MITF accompanied by enhanced activity of NF-κB signaling, and BRAF inhibition in MITF-high, drug-sensitive cells induces a transition to the MITF-low/NF-κB–high state." (PMID 25433395, 2015). "While this further emphasizes the close connection of the MAPK pathway with the regulation of MITF in melanoma cells, the role of SOX10 and FOXD3 in regulating MITF downstream of ERK under physiological conditions in melanocytes is so far unknown." (PMID 25818589, 2015). "CD271 knockdown was found to eliminate the capacity of melanoma cells to form heterogeneous tumors most likely through the downregulation of mediators for melanoma invasion and metastasis (GLI-2, SOX2 and ERBB3), angiogenesis (IGFBP-2), proliferation (FST and MITF) or chemoresistance (RHOJ)." (PMID 25351876, 2015).
melanoma (continued). "PAX3 is activated by PI3 K (phosphatidylinositol 3-kinase) and STAT3 (signal transducer and activator of transcription 3) in melanoma cells, and a negative PAX3-dependent regulation of MITF expression is mediated by BRN2 encoded by POU3F2." (PMID 25433395, 2015). "Applying this model to the MITF‐positive and MITF‐negative populations would predict that melanoma cells reversibly switch between AXL‐/WNT5A‐ and AXL+/WNT5A+ cell populations." (PMID 25818589, 2015). "Remarkably however, the absence of MITF marks a AXL+/WNT5A+ population of melanoma cells – previously identified as the ‘Hoek's invasive signature cohort’ – that is unresponsive to MAPK pathway inhibitors." (PMID 25818589, 2015). "MSCs and slow cycling melanoma cells express low or no MITF, while TACs and proliferative melanoma cells express higher levels." (PMID 26440048, 2015). "Similarly, MITF and BPTF co-repress SASP genes like SERPINE1, IL24, PDGFB, and CYR61 as well as ZEB1 that has a crucial role in melanoma progression." (PMID 26440048, 2015). "Whereas MITF induces cell cycle exit through p16INK4A in melanocytes, cAMP inhibits melanoma cell growth in the absence of p16INK4A." (PMID 25818589, 2015). "SOX10, MITF, and JUN were significantly regulated in melanomas in comparison with cancer." (PMID 26044366, 2015). "While this emphasizes the relevance of BRN2 function for melanoma, the role of MITF was not assessed in this study." (PMID 25818589, 2015). "As MITF expression can be reduced by histone deacetylase inhibitors (HDACi), combined HDAC and MAPK inhibition was shown to prevent MITF-driven resistance in melanoma cells." (PMID 25433395, 2015). "Not surprisingly, MITF expression is also regulated through the microenvironment, and macrophages can induce MITF expression in melanoma cells through secreted TNF‐α." (PMID 25818589, 2015). "We have already shown that different patient-derived melanoma populations grown in vitro in EGF(+)bFGF(+) medium exhibit diverse morphology and molecular characteristics regarding immunophenotype and expression of MITF and MITF-dependent genes." (PMID 26035829, 2015). "We hypothesised therefore that melanoma cells can utilise either CDKN1A/P21 or CDKN1C/P57 to mediate cell cycle arrest induced by MITF and this is reflected in the expression levels of the alternate CDK inhibitors in different melanoma cell lines." (PMID 25755924, 2015). "Of note, IFITM2 expression is upregulated ensuing MITF silencing in melanoma cells (not shown) and deserves to be evaluated as a melanoma initiating cell surface marker." (PMID 25105565, 2014). "Molecular pathways active in the normal melanocyte differentiation program and consisting of MITF and EMT-inducing transcription factors may explain the ability of melanoma cells to easily switch toward an invasive phenotype." (PMID 25538895, 2014). "Melanoma cells resistant to the cytotoxic effects of MEK inhibitors counteracted TGF-β signaling through overexpression of the E3 ubiquitin ligase SMURF2, which resulted in increased expression of the transcription factors PAX3 and MITF." (PMID 24743024, 2014). "Likewise, immunofluorescences showed that SIRT1 mainly localized to the nucleus in melanoma cells and that SIRT1 reduction paralleled that of MITF." (PMID 24742694, 2014). "Together, this suggests the effective use of Axl as a molecular biomarker for MITF-lacking melanomas, in which cells are less differentiated and have higher migratory ability." (PMID 25344858, 2014). "The 3′UTR of MITF mRNA is also a binding site for CRD-BP and this interaction is critical for protecting the MITF transcript from degradation by miR-340, a mechanism believed to be important in melanocytes and malignant melanoma." (PMID 24622399, 2014). "We did not observe changes in expression of the melanoma phenotype determinant MITF during cooperative invasion, thus ruling out the necessity for phenotype switching for invasion." (PMID 25066122, 2014).